ALB (albumin)
Diseases named in the same sentence as ALB in open-access papers (continued):
Sharing a sentence is not in itself a finding about the gene and the disease.
cancer (continued). "The PNI, which is calculated using serum albumin concentration and total lymphocyte count, reflects the nutritional and immunological status of patients with cancer, and is a potential prognostic factor for survival." (PMID 34645392, 2021). "Albumin can be used to reflect the nutritional and systemic inflammatory status of cancer patients and can be used as a prognostic marker for diverse cancers, such as lung cancer, lymphoma, renal cell carcinoma, breast cancer and gastrointestinal cancers." (PMID 33732716, 2021). "The adapted systemic inflammation score (aSIS), calculated from serum albumin and the lymphocyte‐to‐monocyte ratio, has been reported to be a novel prognostic marker for some types of cancers." (PMID 34585051, 2021). "The complexes were then tested against two cancer cell lines, and their protein-binding activities to human serum albumin (HSA) were assessed." (PMID 33805337, 2021). "The CONUT score, which is determined according to the preoperative albumin level in serum, total cholesterol level, and peripheral lymphocyte count, is related to cancer survival and has been proved as the robust inflammatory-related score (17, 30, and 31)." (PMID 34820414, 2021). "It has been reported in many studies that serum ALB levels were significantly correlated with the survival of cancer patients." (PMID 33971833, 2021). "As expected, gemcitabine and paclitaxel were found to be the most effective drugs in the cancer organoid model, whereas gemcitabine plus albumin-bound paclitaxel induced a partial response in the patient." (PMID 33803322, 2021). "Albumin is being investigated extensively in cancer therapy due to its excellent properties as a selective carrier in this type of disease." (PMID 34298666, 2021). "Serum albumin is recognised as a powerful predictor for cancer survival in many types of cancer and it has numerous implications towards postoperative complications and length of hospital stay." (PMID 34732233, 2021). "The serum albumin-based nanovehicle-assisted cancer theranostics, involving gas therapy, chemodynamic therapy (CDT), phototherapy (PTT/PDT), sonodynamic therapy (SDT), and other therapies as well as cancer imaging will be briefly summarized as follows." (PMID 34869202, 2021). "The Glasgow Prognostic Score (GPS) (CRP≤10 = 0, >10 = 1; albumin ≥35 = 0, <35 = 1) is a validated mortality prediction score used in cancer patients." (PMID 34962922, 2021). "Diffusion mechanisms should therefore allow an extensive and effective transport of small molecule RTKI-albumin conjugates and anti-angiogenic therapeutic antibodies from blood to cancer tissues." (PMID 33920299, 2021). "Further studies integrating the advantages of albumin nanocarriers with the modified nucleic acids can be of great potential in cancer therapy." (PMID 34298666, 2021). "Albures 99mTc and Tc-Nanocoll 99 m can be mentioned in nuclear medicine, and albumin is also used as a carrier in the treatment of cancer and viral diseases." (PMID 34051806, 2021). "Abraxane Albumin Formulation Paclitaxel Anti-Cancer Drug Benefits the benefits of albumin in its antitumor function." (PMID 34051806, 2021). "Taken together, this data indicates an association between CTX and the clinical and laboratory features characterizing cancer cachexia, such as BMI, albumin, and CRP." (PMID 34182958, 2021). "In this work, new albumin-based nanoparticles were formulated for the intracellular delivery of doxorubicin with the aim to overcome cancer drug resistance." (PMID 35582009, 2021). "The structural–properties relationships were further explored by molecular docking studies against the enzyme thioredoxin reductase (TrxR), a well-known target for gold complexes in cancer cell lines, and human serum albumin." (PMID 33805337, 2021). "The albumin-to-alkaline phosphatase ratio (AAPR) is a novel promising prognostic marker in cancer patients." (PMID 34885242, 2021).
cancer (continued). "Ag thin films and Ag nanosquare arrays are developed to monitor cancer prognosis due to the correlation between serum albumin levels and prognostic factors, as well as the binding of serum albumin to the surface of these electrodes." (PMID 34835873, 2021). "The PNI, which is calculated based on the serum albumin and circulating peripheral blood lymphocyte count, has been used to assess the immunonutritional status of cancer patients." (PMID 32026332, 2021). "Glucuronidase and enolase activities are quite unusual in albumin, however the latter can be used for differential diagnosis of benign and malignant tumors." (PMID 34638659, 2021). "Meanwhile, albumin is also a valuable biomarker of diverse diseases, including both malignant tumors and benign diseases (liver diseases, inflammation, malnutrition, and diabetes mellitus, etc.)." (PMID 33685425, 2021). "Due to its similar biological function and chemical composition, bovine serum albumin (BSA) as analogue to human serum albumin (HSA) is a widely used component for investigations and developments in the field of drug delivery and cancer diagnostic." (PMID 34207769, 2021). "Combination of the prodrug technique with an albumin nano drug-loaded system is a novel promising approach for cancer treatment." (PMID 34109887, 2021). "Several papers report on the role of albumin levels in plasma and various human diseases such as infections, cancer and even depression in HIV-infected patients." (PMID 34638659, 2021). "The inflammatory biomarker “C-reactive protein to albumin ratio (CAR)” has been reported to significantly correlate to a variety of human cancers." (PMID 33933070, 2021). "One of the most widely used methods of utilizing albumins (e.g., BSA, HSA) as a carrier for nucleic acids in cancer therapy is by encapsulation of the desired nucleic acids into albumin-based nanoparticles." (PMID 34298666, 2021). "The information provided by albumin and Kyn/Trp was integrated in a combined score for cancer exhaustion (CCES)." (PMID 34884980, 2021). "Based on this, it is reasonable to suggest that AGR, an index derived from albumin and globulin, can be used as one of the prognostic factors for cancer." (PMID 33732716, 2021). "First, the levels of serum albumin, which is a chief component of plasma proteins, can reflect the nutritional status, while lymphocytes, which can eliminate cancer cells and are important components of the immune system, can reflect the immunological state." (PMID 33482792, 2021). "An important advantage of our final prediction model is that it includes basic clinical data recorded for all patients (qSOFA), as well as markers that are often routinely measured in patients with a cancer diagnosis (e.g., albumin, lactate dehydrogenase)." (PMID 34439240, 2021). "A low ALI has been revealed by previous studies to be associated with poor prognosis in various cancer types because ALI integrates the factors essential in host immune, nutritional, and systemic inflammation statuses—namely, serum albumin level, BMI, and NLR." (PMID 34660250, 2021). "Patients diagnosed with cancer had significantly lower levels of hemoglobin, albumin and iron, and significantly higher levels of leukocytes, ESR, GGT and ALP, ferritin, TSH, LDH and CRP." (PMID 34555091, 2021). "Albumin is hence being used in pharmaceutical applications as a biocompatible and biodegradable carrier for the delivery of anti-cancer agents, such as chemotherapeutics, biologics, and immunomodulatory drugs." (PMID 34298666, 2021). "Abraxane is a drug formulation based on albumin nanoparticles that sold more than 2 $ billion in 2012 alone and is considered by experts to be one of the main approaches to treating all types of cancer in the near future." (PMID 34051806, 2021). "The cancer cells disappeared after two cycles of chemotherapy with carboplatin and nanoparticle albumin-bound paclitaxel plus pembrolizumab." (PMID 34931476, 2021).
cancer (continued). "In this sense, albumin-based nanocarriers are in the limelight for the successful delivery of chemotherapeutics because of safety, biocompatibility, and specific cancer-targeting properties." (PMID 34208533, 2021). "Decreased albumin level was reported in patients with cancer cachexia compared with weight stable cancer patients or non-cancer controls, and in another study, it was shown to negatively correlate with CRP levels." (PMID 33925872, 2021). "The definite algorithm, called the aMAP score, selected older age, male sex, albumin-bilirubin and low platelet count as cancer predictors." (PMID 33477752, 2021). "We integrated the information provided by measuring the plasma levels of albumin, tryptophan and its metabolite kynurenine in a combined score for cancer exhaustion (CCES)." (PMID 34884980, 2021). "Accordingly, we expected that the binding affinity of the porphyrin derivatives for albumin to affect their accumulation in cancer cells." (PMID 33479459, 2021). "Age, Sex, and variables with p < 0.1 in univariate analysis, such as ECW/TBW ≥ 0.41, active cancer, HR, altered mental status, Hb, albumin, and lactate levels, were included in the multivariable analyses." (PMID 34209962, 2021). "Variables with the lowest completion rates included albumin levels (61.1%), cancer history (74.5%), AM-PAC Activity Score (82.6%), and Fluid and Electrolyte Disorders (83.6%)." (PMID 33556123, 2021). "The GNRI consists of two parameters: serum albumin level and body weight; this index has been reported as a prognostic factor in patients with various cancers, such as gastric cancer, hepatocellular carcinoma, and head and neck cancer." (PMID 33789590, 2021). "Due to the very promising results of biological investigations, the main focus during the next studies will be on the introduction of the active substance (i.e., cytostatic drug) into the developed albumin particles and the analyses using cancer cells." (PMID 34442909, 2021). "Different forms of nanomedicines based on albumin have been investigated for cancer therapy, guided imaging, and biosensors." (PMID 33672770, 2021). "Due to its biocompatibility, low cost and easy preparation, albumin protein-based nanoparticles have been applied for various disease treatments, such as retinal ischemia, liver fibrosis, rheumatoid arthritis, and cancer." (PMID 33407570, 2021). "This superiority of the L/A ratio was also seen in several subgroups such as: lactate ≥2 mmol/L, albumin level less than 30 g/L, cancer patients, diabetic patients, patients older than 65 years of age and when stratifying by infection source." (PMID 34854770, 2021). "Albumin-to-globulin ratio (AGR) has been reported to be a potential prognostic biomarker in several cancers." (PMID 33496841, 2021). "The Glasgow Prognostic Score (GPS) is a simple and well-established nutritional and inflammatory assessment tool for patients with malignancy that incorporates serum albumin (Alb) and CRP23." (PMID 34294776, 2021). "Albumin NPs also show a good affinity for other cancer drugs, such as doxorubicin, curcumin, and tacrolimus." (PMID 35056915, 2021). "The major strength of our study is that PAH-albumin adducts were measured in blood samples collected prior to cancer diagnosis." (PMID 34341437, 2021). "Several studies have found that ALB is a reliable factor for predicting prognosis in different types of cancer, including gynecological cancers, gastrointestinal cancers, hepatocellular carcinoma and esophageal squamous cell carcinoma." (PMID 34692474, 2021). "The HALP, consisting of lymphocyte, albumin, hemoglobin, and platelet, was recently used in patients with several cancers." (PMID 33974528, 2021). "We did not assess confounding factors associated with treatment outcomes and drug exposure such as BSLD and cancer cachexia surrogates (changes in albumin and body weight)." (PMID 34129290, 2021).
cancer (continued). "The fibrinogen/albumin ratio index (FARI) was recently established to evaluate long-term survival in cancer patients based on the finding that a higher FARI was associated with worse prognosis." (PMID 34284775, 2021). "After that, other liposomal formulations were approved by the FDA and albumin-bound nanoparticle for cancer treatments." (PMID 34209111, 2021). "The albumin–globulin ratio (AGR) is also reported as contributive for the prediction of cancer-related prognosis." (PMID 34360768, 2021). "The results revealed higher expression in male patients and its relevance to TNM staging and serum albumin in cancer patients." (PMID 34563222, 2021). "Different types of serum albumin-based nanovehicles for cancer theranostics involve albumin nanoparticles, surface-functionalized albumin nanoparticles, and albumin nanocomplexes." (PMID 34869202, 2021). "Cell viability assay showed that albumin NPs were able to enhance doxorubicin antiproliferative effect in resistant cancer cells in comparison to doxorubicin solution." (PMID 35582009, 2021). "More studies are required to understand the extent of serum albumin and prealbumin level response to nutrition intake despite the metabolic alteration occurring among cancer patients." (PMID 34732233, 2021). "Since then, various studies have reported on the surface modification of albumin nanocarriers with PEG for the delivery of nucleic acids in cancer cells." (PMID 34298666, 2021). "Recent research has demonstrated that serum ALB levels can predict the prognosis of cancer patients." (PMID 34631767, 2021). "Several studies already demonstrated that albumin level alone can predict outcomes across various types of cancer [30, 31, –32]." (PMID 33596518, 2021). "Secreted signaling molecules from cancer cells can trigger lipolysis in CAAs and degraded lipids are smuggled to the cancer cells in a way mediated by lipoproteins, exosomes and serum albumin." (PMID 34888248, 2021). "The Glasgow Prognostic Score (GPS), which is based on serum C‐reactive protein and albumin levels, has been suggested as a reliable prognostic tool for mortality in cancer patients, including NSCLC." (PMID 33480111, 2021). "This article reviews the recent advances on the applications of serum albumin-based nanovehicles in cancer diagnosis and therapy." (PMID 34869202, 2021). "Lymphocytes and serum albumin are significantly closely related to the prognosis of cancer patients." (PMID 33859986, 2021). "Currently, albumin-based drug carriers are considered for application in the treatment of diabetes, infectious diseases and cancers." (PMID 34442909, 2021). "Among them, BMI and serum albumin level are usually used as makers of patients' nutritional status in routine clinical practice, largely due to their abilities to predict cancer patients' survival rates, as indicated in recent studies." (PMID 35096932, 2021). "Five different proteins identified were serum albumin, Heat shock protein 27, gamma actin, squamous cell carcinoma 1 (SCCA-1), and ANXA4 when compared to the control sample." (PMID 34181340, 2021). "Multivariate Cox proportional hazards analysis adjusted for age, malignant tumor, and albumin indicated that a high GBS was an independent predictor of GIB (hazards ratio 2.258, 95% confidence interval 1.326–3.845, p = 0.003)." (PMID 33348860, 2020). "In particular, the GPS, an inflammation-based prognostic score that includes CRP and albumin, is one of the most useful scoring systems for prognosticating patients with various advanced cancers." (PMID 32595832, 2020). "Of these, the pretreatment mGPS, a score combining CRP and serum albumin levels, better predicts cancer survival compared with the peripheral blood cell count-based prognostic scores (e.g., NLR and PLR)." (PMID 32587804, 2020). "A response to serious conditions, such as cancer or cardiovascular disease, leads to decreased synthesis and transcapillary escape of albumin." (PMID 33226880, 2020).
cancer (continued). "A potential candidate for NPs stabilization in the field of nanomedicine and cancer therapy is albumin, which has been successfully applied in Abraxane." (PMID 32733871, 2020). "Degradation of albumin is a source of glutamine, one of the most deprived nutrients in cancer environments." (PMID 33195279, 2020). "DriverPower also called two 3′-UTR driver candidates in total, including TOB1 in pan-cancer and ALB in Liver-HCC." (PMID 32024818, 2020). "The evidence that albumin-bound paclitaxel (nab-paclitaxel) is safe and efficacious for the treatment of many types of malignant tumors is continuously increasing." (PMID 32723378, 2020). "Due to the exceptionally high nutritional requirements of cancer cells, human serum albumin (HSA), an important source of nutrition, accumulates in solid tumors." (PMID 32671070, 2020). "Modification of albumin with PEG has not only improved the blood circulation but also provides a gateway in the pharmaceutical industry for cancer treatment drugs." (PMID 33027891, 2020). "The nanoparticle albumin-bound (nab)-paclitaxel is a solvent-free, colloidal suspension of the taxane paclitaxel, and human serum albumin, already approved for cancer therapy." (PMID 32398657, 2020). "After separation,cancer cells transplanted subcutaneously in nude mice formed tumors, whereas transplanted PHcells in NARs only produced higher albumin levels." (PMID 35111514, 2020). "They galactosylated albumin NPs encapsulated curcumin as carrier (116.24 nm) for HepG2 cancer cell therapy." (PMID 32041140, 2020). "Recent research suggested using in situ albumin targeting for development of carrier-free RNAi-based cancer therapies." (PMID 33003636, 2020). "Elevated C-reactive protein (CRP) (p <0.001), urea (p = 0.002), ferritin (p = 0.01), troponin (p = 0.009), and low albumin (p = 0.02) at presentation were predictors of mortality in the cancer cohort." (PMID 33330085, 2020). "We identified a number of statistically significant variables associated with increased mortality on multivariable modeling including male gender, lower performance status, BMI ≤20, low albumin, as well as cancer-related hospitalization." (PMID 32306924, 2020). "Certain nanomaterials can selectively bind with the receptors on cancer cells, e.g., the interaction of albumin nanoparticles and albumin-binding proteins." (PMID 32582697, 2020). "Albumin is considered to stabilize cell growth and DNA replication, buffer biochemical changes, and maintain sex hormone homeostasis to protect against cancers." (PMID 32245095, 2020). "Albumin is proposed as a carrier for diagnostics and therapeutics that target other diseases than cancer that have altered vascular permeability such as degenerative neurological disorders." (PMID 32960353, 2020). "Patients admitted to the ICU had shorter times from cancer diagnosis, lower hemoglobin, platelet count, creatinine clearance and albumin, and higher LDH upon hospital admission compared to those who remained on the ward." (PMID 33273653, 2020). "Longer prothrombin time, higher D-Dimer, lower albumin, higher neutrophil count can occur in cancer patients, for instance in case of significant hepatic involvement." (PMID 32468851, 2020). "Currently two available forms of liquid paclitaxel exist, a solvent-based (sb-) paclitaxel and an albumin-bound (nab-) paclitaxel, primarily used to treat cancer patients." (PMID 33260517, 2020). "One explanation is that high interleukin-6 levels produced by cancer cells inhibit the synthesis of albumin." (PMID 33028394, 2020). "Albumin is a remarkable carrier with multiple cellular receptor and ligand binding sites, which promotes the delivery of chemotherapy in cancer cells." (PMID 31858848, 2020). "The PNI as the ratio of albumin and lymphocyte reflects both the nutritional and immunological conditions of a cancer patient." (PMID 32245095, 2020).